CD4 (CD4 molecule)
Diseases named in the same sentence as CD4 in open-access papers (continued):
Sharing a sentence is not in itself a finding about the gene and the disease.
tumor (continued). "Expression patterns were further investigated based on the CD4+, CD8+, and CD45+ tumor-infiltrating immune cell categories, ASA, and on tumor extent (T status)." (PMID 37761986, 2023). "Taken together, our present work defines the optimal application scheme and dose of antigen and adjuvants for the non-invasive vaccination platform DIVA leading to tumor protective CD8 and CD4 T-cell responses in a rodent model." (PMID 37727790, 2023). "In our study, we calculated the positive cell density for all biomarkers of immune cells (CD3, CD4, CD8, CD19, and CD163) in both the tumor region and IM." (PMID 37090736, 2023). "DCs are key antigen-presenting cells in the human body and have played an important role as important targets in previous tumor immunotherapy, with the main mechanism being the mediation of tumor immunity through the activation of CD8+ and CD4+ T cells." (PMID 38022585, 2023). "Several studies indicated that the elimination of cholesterol resulted in a notable rise in tumor growth, deterioration of mouse survival, reduction in the quantity of CD8 cells within the TME, and insignificant alteration in CD4 cell levels." (PMID 37801479, 2023). "Among the immune cells that contribute to anti-tumoral responses, conventional T cells (T cells that express an αβ T cell receptor, as well as a co-receptor CD4 or CD8), have attracted the attention of tumor immunologists and clinical scientists." (PMID 37529610, 2023). "Effector T cells, in the form of CD4+ and CD8+ T cells, play a critical role in resolving tumor growth by releasing inflammatory cytokines or by direct lysis of tumor cells." (PMID 37056346, 2023). "Elevated TIM-3 expression occurs substantially on CD4 + and CD8 + T cells infiltrating tumor tissues compared to cells infiltrating adjacent tissues." (PMID 37567938, 2023). "Particularly, the infiltration level of M2-like TAMs negatively correlates with T-cell presence (CD4+T and CD8+T together), supporting the existence of the immunosuppressive effect of M2-like TAMs on immune infiltration at the tumor site." (PMID 38002057, 2023). "Anti-tumor adaptive immune cells include B cells and T cells, with the latter comprising CD8+ cytotoxic T cells and CD4+ helper T cells." (PMID 38066642, 2023). "The TMB, MSI, and tumor microenvironment analysis indicated that SHCBP1 was closely related to immune checkpoints, immune targets, as well as CD4+ naive T cell, CD8+ T cell, and neutrophil." (PMID 36920183, 2023). "The VISTA expression of CD4+ and CD8+ T cells was increased after stimulation and particularly after a coculture with tumor cells." (PMID 37190254, 2023). "This indicates that in the effective treatment group, the expression of immune-related genes of CD4+ and CD8+ cells increased after treatment and the affected genes were different in tumor tissues and blood." (PMID 37762493, 2023). "As the Siglec15 and PD-L1 expression levels influence the tumor microenvironment 15, 30, we were curious regarding CD4+ and CD8+ tumor infiltrating lymphocytes (TILs) in COAD." (PMID 37859817, 2023). "As expected, the lineage markers CD4, CD8, and CD56 were most abundant in the respective immune cell types, and the macrophage marker MRC1 was highest in liver and tumor macrophages." (PMID 37388918, 2023). "For example, a reduction in CD4 + T cells suppresses the activity of cytotoxic T cells in tumors, thereby restricting LUAD tumor cell growth." (PMID 37409245, 2023). "The reduced infiltration of CD4+T and NKT cells, which are key immune cells involved in tumor-killing, in high NUSAP1 tumors also contributes to an immunosuppressive tumor microenvironment 39-41." (PMID 37781040, 2023). "The therapeutic effectiveness of the B16-F10 melanoma tumor was improved by a thermo-sensitive nano-hydrogel co-loaded with DOX, IL-2, and IFN-γ, which boosted tumor cell death and enhanced replication of CD3+/CD4+ and CD3+/CD8+ T cells." (PMID 37102943, 2023).
tumor (continued). "The results of the present study showed that MEX3B and MEX3C expression was positively related to tumour purity and CD8+ T cell and CD4+ T cell infiltration." (PMID 36507941, 2023). "Previous studies have proven that CD4+ and CD8+ T cells comprise functionally and transcriptionally distinct subsets that differ in their capacities to proliferate, anti-tumor effects as well as persistence in vivo." (PMID 37941075, 2023). "The tumor tissues of mice that underwent exercise intervention presented a remarkable increase in CD3+/CD8+ T lymphocytes and a considerable decrease in CD4+/CD25+ T lymphocytes." (PMID 37876940, 2023). "In agreement with previous studies, we found the CD4+ population to be reduced, whereas the CD8 + PBMC population was seen to be increased in the tumor population." (PMID 38092866, 2023). "Our immunohistochemical study showed that administration of B. longum 420 increased the infiltration of both CD4+ T cells and CD8+ T cells into the tumor tissues." (PMID 37340017, 2023). "We found that depletion of CD8+ T cells or both CD4+ and CD8+ T cells significantly reversed the tumor regression induced by EHBP1L1 knockdown, whereas depletion of CD4+ T cells alone, had no such effect similar to the IgG control." (PMID 36775874, 2023). "In the survival analysis, we found that patients who had CD4+ and CD8+ T cells or their PD-1− subsets located nearer to tumor cells at baseline experienced worse OS and PFS." (PMID 37275884, 2023). "MEX3C correlated not only with tumour purity but also with CD8+ T cell, CD4+ T cell, macrophage, and neutrophil infiltration." (PMID 36507941, 2023). "The recently study reported that IL-26 is involved in the production and promotion of MPE by enhancing CD4+IL-22+ T-cell differentiation and inhibiting CD8+ T-cell tumor-killing activity." (PMID 36776832, 2023). "The combination of CD4+ T cell depletion and PD-L1 blockade significantly increased the proportion of CD44+CD69+CD8+ T cells in CT26 tumor tissues." (PMID 36969495, 2023). "Compared to controls, the percentage of both T helper cell memory (CD4 + CD44hi) and antigen-exposed cytotoxic memory cells (CD8 + CD44hiCD49d +) were significantly higher in mice recovered from both tumor types in the LNs as well as in the spleens." (PMID 37118819, 2023). "In this study, we verified that GPR84 knockout did not change the proportions of MDSCs, macrophages, B cells, NK cells, CD4+T cells and CD8+ T cells in tumor-free mice." (PMID 37105980, 2023). "The advantage of HSP vaccine, compared to other tumor vaccines, is its highly specificity of the interaction between HSPPC-96 and APCs, and therefore, better eliciting robust CD4 + and CD8 + T-cell immune responses." (PMID 37046332, 2023). "Specifically, we highlight the cell signature, differentiation trajectory, regulatory mechanisms, and contributions to anti-tumor immunity of exhausted CD8+ T cells, as well as the roles of CD4+ T cells in helping CD8+ T cell responses." (PMID 37332039, 2023). "While tumor killing was considered to be CD8+ T cell function, the majority of previous understanding of the functionality of CD4+ T cells came from studies about anti-viral immunity." (PMID 37063862, 2023). "Chaurio and colleagues identified that TLS formation was dependent on the CXCL13 pathway in CD4+ T cells, with blocking CXCL13 hindering TLS assembly and subsequently promoting tumor growth." (PMID 38111571, 2023). "This treatment led to a noticeable increase in the infiltration of CD4+ and CD8+ T cells at the tumor site." (PMID 37892972, 2023). "To this end, we utilized immunohistochemistry with custom-made VisioPharm (Version 2018.4) analysis apps to determine the percent of total tumor area with immunoreactivity to CD68, CD3, CD4, CD8a, neutrophil elastase, and CD45r." (PMID 38136319, 2023).
tumor (continued). "Cytotoxic properties are essential for effector cell-mediated killing of infected and tumor cells - a cellular characteristic primarily ascribed to NK cells, CD8+ T cells and a subset of CD4+ T cells." (PMID 37664600, 2023). "Fn significantly reduced the αPD-L1-mediated increase in CD4+CD3+ and CD8a+CD3+ cells and the activity (GZMB+) of the infiltrated CD8a+ T-cell population in the tumor region." (PMID 37723150, 2023). "Upon binding to its receptor (expressed on CD4+, CD8+T-cells and NK-cells), IFNγ can trigger biologically relevant anti-tumor activities." (PMID 36839699, 2023). "Dendritic cell (DC) therapy is intended to induce the proliferation of T cells and promote the activation of CD4+ and CD8+ T-cells by presenting them with tumor antigens, allowing CD8+ T-cells to infiltrate the tumor microenvironment." (PMID 38136333, 2023). "Tumor control, and induction of reactive CD8+ and CD4+ T cells, are among the main readouts for determining the efficacy of TCVs." (PMID 37720215, 2023). "IHC staining revealed that Tfap2a decreases Pdl1 expression but improves the density of Cd4+ and Cd8+ T cells in B16F10 tumor cells." (PMID 37330579, 2023). "Both CD4+ and CD8+ T cell compartments were efficiently activated as tumor-naïve (Ctrl) PBMCs and displayed similar cell frequencies (respectively)." (PMID 38235131, 2023). "The results of previous studies utilizing genetically engineered mouse models and our examination of human PDAC specimens suggested that a decrease in tumor-stromal collagen in PDAC negatively affected the anti-immune system, such as CD4+ and CD8+ TILs." (PMID 37477731, 2023). "While in detail, exhausted CD8+T and CD4+T cells were increased, and XCL2+NK and FGFBP2+NKT cells were decreased in LN+AM compared to those in LN−AM, indicating a compromised anti-tumor TME." (PMID 38065972, 2023). "Last, NvIH enhanced the fraction of circulating CD4+ and CD8+ T cells and cytokine-secreting (IFN-γ, TNF-α) CD4+ and CD8+ T cells, which contributed to the protective immunity against tumor rechallenge." (PMID 37450588, 2023). "Meanwhile, it was also found that the nanoprobes can promote the recruitment of CD4+ and CD8+ T cells to inhibit the tumor growth through the cytokines secretion." (PMID 36597067, 2023). "We show that the tumour growth control exerted with combined olaparib and AD1775 treatment was abrogated when both CD8+ and CD4+ T cells were depleted." (PMID 37582853, 2023). "A statistical difference was found in the CD4+ (p = 0.0038) and CD45+ (p = 0.0465) tumor-infiltrating immune cell percentages, platelet count (p = 0.0408), and ASA performance scores (p = 0.0217) of the patients." (PMID 37761986, 2023). "On the other hand, infiltrated CD4 + and CD8 + T lymphocytes, and natural killer (NK) cells are key anti-tumor cells that suppress the proliferation of malignant cells." (PMID 37221555, 2023). "More specifically, we estimated 28 immune cell types infiltrating and observed a lower proportion of tumor‐infiltrating lymphocytes (TILs) in the MS1 cohort, including activated CD4+ T cells, natural killer T cells, type 2 T helper cells, and eosinophils." (PMID 38868430, 2023). "Exercise-induced growth inhibition was associated with significantly higher levels of intra-tumoral CD4+ T cells, CD8+ T cells, NK cells and DCs, indicating a shift towards an anti-tumor microenvironment." (PMID 37760634, 2023). "Paradoxically, a recent study demonstrated that TIGIT was expressed on 53% and 28% of CD8+ and CD4+ T cells, respectively, within PDAC tumor-infiltrating lymphocyte populations." (PMID 37649613, 2023). "The mean clone fractions of the top 3 clones was 5-fold higher for CD4 T-cells and 8-10 fold higher in CD8 T-cells in tumor-cured mice compared with virus control mice." (PMID 37033929, 2023). "In LUSC, PUS1 has significant correlations with tumor purity, B cells, CD8+ T cells, CD4+ T cells, macrophages, neutrophils, and dendritic cells." (PMID 37925171, 2023).
tumor (continued). "CD8 T cell (CD3 + CD8+) densities within tumor regions after SBRT were decreased 2.22-fold (p = 0.001) relative to densities before SBRT, while CD4 T cell (CD3 + CD4+) densities, and Treg cell (CD4 + FOXp3) densities remained largely unchanged." (PMID 35058580, 2023). "Specifically, both Tfh and memory B cells advance the anti-tumor cellular and humoral immunities by promoting a chemokine-mediated CD8+ T cell and B-cell infiltration and contributing, as APCs, to additional CD4+ T cell expansion, intratumorally." (PMID 37894300, 2023). "Cluster C3 exhibited lower levels of conventional anti-tumor immune cells, including activated B cells, CD8+ T cells, CD4+ T cells, and NK cells, as compared with C1 and C2." (PMID 37691826, 2023). "In mice intraperitoneally infected with the transgenic parasites, NY-ESO-1-specific CD4+ and CD8+ T cells were generated, triggering a range of MyD88- and IL-12-dependent tumor-specific humoral and cellular immune responses." (PMID 38274735, 2023). "Neoadjuvant anti-LAG-3/anti-PD-1 treatment mediated tumor infiltration by memory CD4+ and effector CD8+ T cells in the post-treatment tumor specimens of patients with favorable treatment response." (PMID 36674809, 2023). "Research conducted on CT26 models has demonstrated that regulatory T cells (Tregs) with high levels of TIM3+ accumulate in the tumor microenvironment prior to the exhaustion of CD8+ and CD4+ T cells." (PMID 37376141, 2023). "At the cellular level, tumor cells of AITL vary in size (small to medium) and are mature αβ CD4+ and CD8+ T cells." (PMID 37746258, 2023). "Upon examination of the CD3+ population, a significant enrichment of CD4+ and CD8+ T-cells within the tumour compartment at D7 was observed in mice that had received VSVΔ51+T-DM1, compared to those that received monotherapies or PBS control." (PMID 37153626, 2023). "CD8+ T cells and CD4+ T cells are both types of CTL and are believed to have a dominant role in producing an effective anti-tumor response." (PMID 37180714, 2023). "We subsequently conducted the visualization of the communication landscape between CD4 + and CD8 T + cells and tumor cells, respectively, and extracted the core receptor-ligand pathway for further analysis." (PMID 36765369, 2023). "Treg cells are recruited to the tumor foci by chemokines such as CCL22 in the tumor microenvironment, while CD4+ and CD25+ T cells are converted to Treg cells by specific cytokines." (PMID 36923251, 2023). "The tumor‐bearing mice were treated with a single infusion of GCT02 or EV T cells at a 1:1 CD4+:CD8+ ratio, and tumor size was monitored weekly." (PMID 36890859, 2023). "CD3+, encompassing both CD8+ and CD4+ T-helper cells, and CD8+ cells also have different densities in different areas of the tumor, and the evaluation has to be performed twice for each of these markers on consecutive slides." (PMID 37627073, 2023). "Tumor-infiltrating lymphocytes (TILs) in BMs are usually composed of different subsets of CD8+ T cells and CD4+ T cells, including T-regulatory cells (Tregs)." (PMID 37876939, 2023). "We sequenced 201 CD4 + T cells in tumor tissues from TOP2A vaccinated mice and 57 CD4 + T cells in tumor tissues from the CpG control mice." (PMID 37880313, 2023). "Flow cytometric analysis also showed that combination therapy increased the populations of infiltrated CD4+ T cells, CD8+ T cells, IFN-γ+ CD4+ T cells and IFN-γ+ CD8+ T cells in the tumor immune microenvironment." (PMID 37291128, 2023). "After functional depletion of CD4+ T and CD8+ T cells in 4T1 tumour-bearing BALB/c mice, the antitumour effects disappeared in TIOs+NIR3-treated mice." (PMID 37673934, 2023). "Bioinformatic analysis of tissues from gastric cancer patients also revealed that the degree of infiltration of CD8+ and CD4+ T-cells, macrophages and DCs was positively correlated with the expression of FGFR1 in tumor cells." (PMID 36966334, 2023).
tumor (continued). "TCRa−/− mice, which lack CD4+ and CD8+ T cells, showed an intermediate phenotype in which tumor growth was still slowed significantly over PBS treatment." (PMID 36881506, 2023). "Dendritic cells derived exosomes can more effectively stimulate CD4+ helper T cells and CD8+ CLTs proliferation and induce an anti-tumor immune response, representing a novel immunotherapy method for ovarian cancer patients." (PMID 37497408, 2023). "HLA Class I and II are cell-surface molecules that bind with and present tumour antigens to CD8+ and CD4+ T cells to signal cell death and antibody production, respectively." (PMID 39516396, 2023). "The correlation of tumor purity as well as the expression of the top eight HR genes with six infiltrating immune cells (including CD8+ T cells, CD4+ T cells, B cells, dendritic cells, macrophages, and neutrophils) were analyzed." (PMID 38004399, 2023). "In tumor‐bearing mice, blockade of IL‐6 promoted the infiltration of CD8+ T cells and IFN‐γ+CD4+ T cells and sensitized anti‐PD‐1 therapy." (PMID 38020717, 2023). "The significant increases in the percentage of CD4+ and CD8+ T cells in spleens of 4T1 tumor–bearing mice were observed following pharmacogenetic inhibition of CeMCRH neurons." (PMID 37847562, 2023). "Treg cells in the tumor microenvironment can restrict the activation and development of CD4 helper T cells and CD8 cytotoxic T cells via a variety of mechanisms, resulting in diminished tumor antigen-expressing responsiveness and immunological escape." (PMID 37476838, 2023). "On the contrary, M1 TAMs produce proinflammatory cytokines, such as TNF and IL-12; recruit Th1 CD4+ T cells through CXCL9 and CXCL10 secretion; and induce direct tumor cell killing." (PMID 37377970, 2023). "In HBV-related HCC, cytotoxic CD4+ T cells present similar numbers with cytotoxic CD8+ T cells, while they are less effective to eliminate tumor cells due to secreting less cytolytic factors such as granzyme A (GzmA) and granzyme B (GzmB)." (PMID 38090482, 2023). "The main challenge is the incorporation of multiple epitopes recognized by CD4+ and CD8+ cells, considering tumor heterogeneity." (PMID 37686485, 2023). "To investigate the anti-tumor activity of CD4+ CTLs in OSCC, we compared the expression level of cytotoxic genes between the CD4+ CTL subset and other cytotoxic T cell subsets." (PMID 38077321, 2023). "Among all patients with CODEX data, a positive correlation between the expression of CD45 and CD44, CD4 and CD45 inside tumor was observed (R > 0.9, p < 0.0001)." (PMID 38223688, 2023). "The total infiltrating CD3+ T-cell population as well as the CD4+ and CD8+ subpopulations were labeled in huPDX sequential tumor sections." (PMID 36860657, 2023). "Consistent with a protective role of GPR15, administration of GPR15L to established tumors in the MC38-CRC model increased CD45+ cell infiltration, enhanced TNFa expression on CD4+ and CD8+ T cells at the tumor site and dramatically reduced tumor burden." (PMID 38074634, 2023). "Only active CD4+, effector memory T (Tem CD4+), type 2 T helper (Th2), and memory B lymphocytes positively correlated with ZNF714 level across various tumor types." (PMID 37958512, 2023). "According to the TIMER database analysis, OX40 was correlated with CD4 + T cells, neutrophils, and dendritic cells infiltration, suggesting that OX40 was also correlated with tumor immune microenvironment." (PMID 37024802, 2023). "While stimulation with GITR ligands promoted expansion and effector functions of both CD4 and CD8 TILs, TH9 responses further contribute to their anti-tumor activity." (PMID 37189417, 2023). "Previous studies have shown that TACE increases the number and activity of CD4+ and CD8+ T cells by stimulating necrotic tumor tissue, which promotes an improvement in the immune microenvironment." (PMID 37012542, 2023).